TBK1 (TANK binding kinase 1)
Diseases named in the same sentence as TBK1 in open-access papers (continued):
Sharing a sentence is not in itself a finding about the gene and the disease.
glaucoma (39 papers, 2012 to 2026). Increased pressure in the eyeball due to obstruction of the outflow of aqueous humor. "Studies focused on understanding the contribution of these mutations to glaucoma have revealed that some of these mutations, E50K and M98K specifically, result in modified interactions with TBK1 that influence the pathogenic activity of OPTN." (PMID 41567509, 2025). "On the other hand, the gain-of-function mutation and copy number variation (CNV) of the TBK1 gene have been proposed as possible Normal Tension Glaucoma (NTG, a POAG subtype) causing mechanism." (PMID 38152303, 2023). "Duplication of TANK-binding kinase 1 (TBK1) genes induced by optineurin mutations plays a significant role in glaucoma." (PMID 30364320, 2018). "TBK1 mutations have also been identified to cause ALS, while TBK1 gene duplications have been linked with glaucoma." (PMID 29971063, 2018). "The Optn effector TBK1 is also a glaucoma-associated protein involved in macroautophagy and mitophagy, and shows increased interaction with E50K-Optn." (PMID 29971063, 2018). "TBK1 encodes a kinase that phosphorylates OPTN and stimulates autophagy and mutations in TBK1 or OPTN appear to cause glaucoma via dysregulation of autophagy." (PMID 27275741, 2016). "The familial primary open-angle glaucoma-associated E50K Optn mutant was reported to bind with higher efficiency to TBK1 and the development of open angle glaucoma was observed in the course of interferon alpha therapy for chronic hepatitis B." (PMID 25923723, 2015). "We also show that Tbk1, a glaucoma-associated protein, through its catalytic activity, induces death in retinal cells and this requires autophagic function of OPTN." (PMID 26376340, 2015). "In conclusion, our results show that a glaucoma-associated mutation, M98K, of optineurin enhances its phosphorylation at Ser177 by activating Tbk1 protein kinase." (PMID 26376340, 2015). "Besides MYOC (myocilin), at least two Mendelian glaucoma genes, TBK1 (TANK-binding kinase 1) and OPTN (optineurin), encode proteins that directly regulate PINK1–PARKIN signaling and LC3 (microtubule-associated protein 1A/1B-light chain 3) recruitment." (PMID 41516357, 2026). "Interestingly, an OPTN E50K mutation was identified in familial primary open-angle glaucoma that promotes stronger interactions with TBK1, which in turn triggers an accumulation of insoluble OPTN and constriction of the Golgi body." (PMID 38287189, 2024). "Moreover, a glaucoma-associated mutated OPTNE50K enhances its interaction with TBK1 but reduces autolysosomes, and polyubiquitin binding to OPTN is required for optimal activation of TBK1 and production of IFN-β." (PMID 37352355, 2023). "In addition, duplication of TBK1 can cause glaucoma, for the reason that increased transcription of TBK1 encodes a kinase that phosphorylates OPTN, which recruits LC3B and initiates autophagy." (PMID 36589756, 2022). "However, neurodegeneration in ALS and glaucoma have also been linked to other TBK1- and Optn-related biological processes, including xenophagy, inflammation, and innate immunity [reviewed in Ref." (PMID 29971063, 2018). "The utility of these TBK1 inhibitors may be explored for M98K-OPTN associated glaucoma also because M98K-OPTN induced retinal cell death is inhibited strongly by a TBK1 inhibitor." (PMID 29951055, 2018). "Indeed, mutation E50K of optineurin, a critical regulator of antiviral signaling, promotes interaction with TBK1 and is associated with familial primary open-angle glaucoma." (PMID 27454487, 2016). "Thus, it appears that these two glaucoma-associated proteins, TBK1 and OPTN, regulate each other’s activity to induce autophagy mediated cell death signalling." (PMID 26376340, 2015). "This suggests that TBK1-associated glaucoma may be caused by dysregulation (over-activation) of this catabolic pathway." (PMID 24883232, 2014).
glaucoma (continued). "Duplication of TBK1 gene in NTG patients has been shown to cause increased transcription of TBK1, suggesting that this form of glaucoma may be caused by stimulation of autophagy." (PMID 24883232, 2014). "Investigators found TBK1 expression in several relevant areas of glaucoma pathology – retinal ganglion cells, the nerve fiber layer, and microvasculature of the retina." (PMID 41567509, 2025). "Beyond glaucoma, these processes overlap with mechanisms observed in broader neurodegenerative diseases, reinforcing TBK1’s significance as a therapeutic target." (PMID 41567509, 2025). "The IOP independent primary genetic glaucoma model reassembles normal tension glaucoma (NTG) and involves genetic mutation within Tbk1 and Glast genes." (PMID 38562304, 2024). "Mutations in the Tbk1 gene have been linked to NTG, a form of glaucoma that manifests with low or average IOP." (PMID 38562304, 2024). "Pathogenic variants in TBK1, MYOC, and OPTN are associated with primary open-angle glaucoma (POAG) with severe visual field defects." (PMID 39669598, 2024). "Glaucoma, especially its intricate variants, is linked to variants in genes like MYOC, OPTN, and TBK1." (PMID 39766826, 2024). "The three Mendelian genes, myocilin, TANK-binding kinase 1 (TBK1) and optineurin (OPTN), have been linked to glaucoma, with the last two genes being mitophagy-related genes." (PMID 37566048, 2023). "TBK1 is the binding partner of optineurin, an established glaucoma gene, and copy number variants in TBK1 have been associated with normal tension glaucoma (NTG) most commonly as well as primary open-angle glaucoma (POAG)." (PMID 34258050, 2021). "Among genes implicated in glaucoma, either by GWAS or as rare Mendelian alleles, most were expressed predominantly within RGCs (e.g., OPTN, TMCO1, TBK1)." (PMID 32555229, 2020). "Genetic alterations in TBK1 (also known as NAK or T2K) were initially associated with diseases with known neuroinflammatory components, including two forms of glaucoma: primary open angle glaucoma and normal tension glaucoma." (PMID 28148298, 2017). "Recently, studies of glaucoma have identified disease-causing genes (OPTN and TBK1) that directly interact with each other in the same biological pathway." (PMID 27275741, 2016). "TBK1 phosphorylates OPTN and glaucoma-causing mutations in OPTN have been shown to alter the interaction between TBK1 and OPTN." (PMID 24883232, 2014). "Linkage analysis of large pedigrees with Mendelian forms of glaucoma has identified three genes that cause glaucoma (MYOC, OPTN, and TBK1)." (PMID 24883232, 2014). "More, recently, Minegishi and coworkers reported that the over-expression of a glaucoma causing-mutation in OPTN, Glu50Lys, produces an accumulation of insoluble OPTN protein that can be blocked with chemical inhibition of TBK1 activity in HEK293 cells." (PMID 24883232, 2014). "Its roles in the NF-κB and IRF signaling pathways, as well as its influence on mitochondrial function and cellular stress responses, establish TBK1 as a key contributor to neurodegenerative mechanisms, including in the context of glaucoma, and particularly NTG." (PMID 41567509, 2025). "Understanding TBK1’s complex contributions to glaucoma pathogenesis could pave the way for innovative therapies aimed at preserving vision and halting neurodegeneration." (PMID 41567509, 2025). "Based on these results, TBK1 could be either inhibiting or increasing inflammation and apoptosis in glaucoma." (PMID 41567509, 2025). "TBK1, OPTN, and ATXN2 variants all cause familial ALS but also glaucoma." (PMID 38658168, 2024). "OPTN, TANK binding kinase 1 (TBK1), and Myocilin (MYOC) are genes linked to glaucoma." (PMID 36589756, 2022). "Despite TBK1 immune regulatory capacity, direct inflammatory effects derived from the glaucoma-associated TBK1 duplication have not been documented to date." (PMID 33953963, 2021). "The mechanism of TBK1-mediated glaucoma largely remains to be elucidated." (PMID 34258050, 2021).
glaucoma (continued). "The TBK1 protein kinase has emerged as a potential drug target for E50K-OPTN induced glaucoma." (PMID 29951055, 2018). "Consequently, defects in TBK1 or OPTN and autophagy are a plausible cause of the retinal ganglion cell death and optic nerve damage that are central features of glaucoma." (PMID 27275741, 2016). "Since TBK1 has shown both pro-inflammatory and anti-inflammatory actions and there is a lack of research indicating how TBK1 duplications may affect mitophagy, there is an obvious need to continue research on this kinase in glaucoma." (PMID 41567509, 2025). "However, the mechanism of TBK1-mediated glaucoma largely remains to be elucidated." (PMID 34258050, 2021). "WD repeat domain 36 (WDR36), neurotrophin 4 (NTF4), ankyrin repeat and SOCS box-containing 10 (ASB10), and TANK-binding kinase 1 (TBK1) are other genes that have also been reported to be glaucoma-causing genes, but are controversial or have not yet been widely replicated." (PMID 22509100, 2012). "Through literature review, several key glaucoma-related genes were identified, including MYOC, TBK1, COL1A1, COL1A2, FOXC1, LRP2, OPTN, and TEK." (PMID 40808675, 2025). "This study therefore elucidates a novel mechanism whereby TBK1 regulates p16 expression and RGC senescence, suggesting a potential novel treatment strategy for minimizing RGC senescence in retinal ischemia and glaucoma." (PMID 28425986, 2017). "Although initial studies have shown that TBK1 is expressed in human RGCs and in tissues affected by glaucoma, the role of TBK1 in RGCs and in the pathology of RGC senescence in glaucoma remains an unanswered question." (PMID 28425986, 2017). "Interestingly, these glaucoma-related genes like MYOC, TBK1, COL1A1, COL1A2, FOXC1, LRP2, and TEK also showed significant differential expression in RCC tissues." (PMID 40808675, 2025). "Collectively, we concluded that the glaucoma patients in this study do not have TBK1 duplications or triplications." (PMID 39669598, 2024). "In our previous studies, we observed that the TBK1 inhibitor BX795 and Tbk1 siRNA prevent via p16INK4a inhibition RGC senescence in a mouse model of glaucoma, thus, providing a promising target for a molecular glaucoma therapy." (PMID 30364320, 2018). "Another glaucoma-associated variant of OPTN, M98K, induces cell death and Tbk1-dependent phosphorylation selectively in RGC-5 cells but not in IMR32 or HeLa cells." (PMID 29203899, 2017). "Moreover, our findings indicate that suppression of the TBK1/Akt Ser473/Bmi1 Ser316/p16 axis is a potential therapeutic strategy for minimizing RGC senescence in retinal ischemia and glaucoma." (PMID 28425986, 2017). "Unlike the glaucoma-causing mutation of TBK1, which is actually a gene duplication leading to overexpression, ALS-FTD mutations disable TBK1 function, underscoring the complex pathologies that can be induced by altering normal function of the TBK1-OPTN axis." (PMID 34201955, 2021). "However, in mouse models of glaucoma, it is still unclear whether ABCA1 participates in ANXA1 membrane translocation, and whether and how blocking TBK1 directly protects against RGC apoptosis." (PMID 30364320, 2018). "The same applies to glaucoma, where complex Mendelian and non-Mendelian genetic mechanisms coexist, with multiple loci, such as MYOC, OPTN, and TBK1, each contributing to the variability and progression of glaucomatous neurodegeneration." (PMID 39766826, 2024).
lung cancer (32 papers, 2012 to 2025). A malignant neoplasm involving the lung. "Studies have shown that TBK1 is also associated with cancers, such as kidney cancer, cervical cancer, and lung cancer." (PMID 35574315, 2022). "First, it was shown that TBK1 is highly expressed in lung, breast, and colon cancer and is mutated (P675L) in lung carcinoma." (PMID 29971063, 2018). "Studies on lung cancer have also shown that TBK1 signaling was essential for the survival of KRAS-driven lung cancer cells, which is dependent on TBK1-AKT/mTOR signaling-mediated tumor growth and immunosuppression." (PMID 40076567, 2025). "Treating lung cancer models with RBN2397 promotes TBK1 phosphorylation of IRF3, restores type I IFN signaling, and enhances tumor immunogenicity." (PMID 37077937, 2023). "They found that TBK1 knockdown decreased metadherin phosphorylation at Ser568, which suggested metadherin as a downstream effector of TBK1 in lung cancer cell’s survival." (PMID 36307391, 2022). "Mass spectrometric analysis of TBK1 knockdown in lung cancer cells identified 385 proteins with altered phosphorylation." (PMID 35395857, 2022). "For example, in a mouse model with KRas-activated lung cancers, Tbk1 induces local immunosuppression by facilitating EGF-induced PD-L1 expression on tumor cells." (PMID 35395857, 2022). "The relationship between growth factor signaling and TBK1 activity appears to be complex and context dependent, however, as growth factors were shown recently to activate TBK1 (i.e., increase TBK1 P-S172) in lung cancer cells (see Discussion)." (PMID 34245780, 2021). "TBK1 was shown to be co-lethal in KRAS mutant lung cancer and it has been investigated as a potential target in triple-negative breast cancer." (PMID 27613601, 2016). "Accordingly, it was recently found that TBK1 is activated at mitosis in A549 cells and that loss of TBK1 impaired mitotic phosphorylation of the mitotic Polo-like kinase 1 (Plk1) in TBK1-sensitive lung cancer cells." (PMID 25923723, 2015). "Activation of TBK1 at mitosis was previously reported and further shown to promote phosphorylation of Plk1 and metadherin in TBK1-sensitive lung cancer cells to maintain their survival." (PMID 25923723, 2015). "Our findings suggest that MEKi activates the cGAS-STING-TANK-binding kinase 1-nuclear factor kappa B-CXCL10 axis post-radiotherapy in KRAS-mutant lung cancer, increasing T-cell infiltration and function, activating anti-tumor immunity, and inhibiting tumor growth." (PMID 41368644, 2025). "We therefore performed 24-h SCH772984 treatment of A549 KRAS G12S mutant lung cancer cells, where we observed a loss of IKKε, but not TBK1 protein levels." (PMID 40738190, 2025). "Additionally, we observed a significant increase in phosphorylated STING and phosphorylated TBK1 levels in the MEKi+RT group across the three KRAS-mutant lung cancer cell lines." (PMID 41368644, 2025). "TBK1 is also a central mediator of growth factor signaling in lung cancer tumorigenesis." (PMID 39279883, 2024). "Inhibition of TBK1 resulted in decreased cell viability and proliferation of lung cancer cells." (PMID 36988258, 2023). "Although TBK1-mediated regulation of PD-L1 has been reported in lung cancer, the role of TBK1 in controlling PD-L1 expression in G.C. remains unclear." (PMID 37357254, 2023). "Our previous study revealed that TANK-binding kinase 1 (TBK1) regulates EMT in lung cancer cells." (PMID 30988282, 2019). "Additionally, our previous study confirmed that TBK1 promotes radiation-induced Type 3 EMT in lung cancer A549 cells." (PMID 30988282, 2019). "TBK1 was described as co-synthetic lethal in KRAS mutant lung cancer but, so far, it has not been associated with EGFR mutant cancer." (PMID 27613601, 2016). "Furthermore, it has been suggested that TBK1 functions as a negative regulator of cell growth in lung cancer." (PMID 25309543, 2014).
lung cancer (continued). "TBK1 with S716A mutation failed to rescue the growth defect of TBK1-knockdown A549 cells both in vitro and in vivo, suggesting that phosphorylation of Ser716 is critical for the oncogenic function of TBK1 in lung cancer progression." (PMID 39279883, 2024). "Moreover, Syk impairs the activation of TBK1 in lung cancer cells infected with influenza A virus." (PMID 39493293, 2024). "Consistent with this, TBK1 promotes anti-apoptotic signaling by activating the NF-κB signaling pathway, which also plays a crucial role in the survival of KRAS-mutant lung cancer cells." (PMID 40076567, 2025). "Further studies based on mouse lung cancer models and human cancer cell lines demonstrated that TBK1 signaling-regulated CCL 5 and IL-6 promote KRAS-driven NSCLC by affecting lung cancer cell proliferation and the local inflammatory microenvironment." (PMID 40076567, 2025). "YAP1 upregulation was further identified as a mediator of resistance to combined TBK1 and MEK inhibition in KRAS mutant lung cancer cells and in a KRAS G12D mutant genetically engineered lung cancer mouse models." (PMID 34685695, 2021). "This circuit appears to be mediated by IKK-related kinases TBK1 and IKKε, as the inhibition of JAK2/TBK1/IKKε leads to the disruption of this circuit and impairment of lung cancer growth." (PMID 33116132, 2020). "The importance of RALB and TBK1 to RAS-induced lung cancer was confirmed in a RNA inhibitor screen of synthetic lethal partners of oncogenic KRAS, where RALB and TBK1 were identified as top targets." (PMID 31681587, 2019). "TBK1 is vital for type I interferon production during antiviral immune responses and acts as an oncogene in cancer cells, regulating cell division, autophagy, and AKT pro-survival signaling in melanoma and lung cancer." (PMID 39001398, 2024). "cGAS expression showed no expression difference among lung cancer types, while TBK1 and IRF3 showed a low downregulation only in SCLC tumour samples." (PMID 35794238, 2022). "It is important to note, however, that stimulation of human A549 lung cancer cells and primary mouse lung cancer cells with several different growth factors (e.g., EGF; FBS; insulin) increased TBK1 S172 phosphorylation, which required TBKBP1 (TBK1 binding protein 1), a TBK1 adaptor protein." (PMID 34245780, 2021). "TANK Binding Kinase 1 (TBK1) is a non-canonical IκB kinase that contributes to KRAS-driven lung cancer." (PMID 26656453, 2015). "Furthermore, TBK1 activity is selectively essential for the survival of cancer cells with mutant KRAS, identified in a systematic synthetic lethal RNAi screening in NCI-H23 cells, a lung cancer cell line expressing mutant KRAS." (PMID 39279883, 2024). "However, despite the biological plausibility of combination TBK1/MEK inhibition as an anticancer therapy, resistance to this regimen develops rapidly in mouse models of KRasG12DLbk1null and KRasG12DTrp53null lung cancers due to the epigenetic-mediated upregulation of IGF1 and YAP1." (PMID 35395857, 2022). "For example, TBK1 inactivation reduced S6K1 T389 but not Akt S473 phosphorylation in response to growth factors in A549 human lung adenocarcinoma cells or primary mouse lung cancer epithelial cells." (PMID 34245780, 2021). "In a mouse model of lung cancer, the adaptor protein, TBK-binding protein 1 (TBKBP1), has been shown to mediate PKCθ direct phosphorylation of TANK-binding kinase 1 (TBK1) in response to epidermal growth factor (EGF) stimulation, leading to the activation of the oncogenic activity of TBK1." (PMID 33562506, 2021). "In search of TBK1 substrates responsible for survival in lung carcinoma, it was found that TBK1 phosphorylates the mitotic kinase PLK1, suggesting that TBK1 could regulate mitosis to drive lung cancer cell survival." (PMID 29971063, 2018). "Whether TBK1 plays a role in EGFR mutant lung cancer is currently not known." (PMID 27613601, 2016).
lung cancer (continued). "However, our previous findings suggested a lack of crosstalk between TBK1 signaling and the TGF-β/Smad pathway in radiation-induced EMT in lung cancer A549 cells, and a previous study has shown that ERK is less likely to be involved in TGF-β-induced human alveolar EMT44." (PMID 30988282, 2019).